KRAS (KRas proto-oncogene, GTPase)
Diseases named in the same sentence as KRAS in open-access papers (continued):
Sharing a sentence is not in itself a finding about the gene and the disease.
tumor (continued). "We can hypothesize that the KRAS G12C mutation could be present in a non-preponderant tumour subclone." (PMID 31344983, 2019). "Regardless, SHOC2’s contribution to tumorigenic properties in some RAS-mutant human cells lines, as well as to tumor development in a KRAS-driven mouse LUAD model suggests targeting SHOC2 in the clinic may have activity as monotherapy against a subset of RAS-mutant cancers." (PMID 31182717, 2019). "Moreover, we found that miRNA-27a could restore the tumor inhibition effect of cetuximab in KRAS-mutant CRC cells." (PMID 31717759, 2019). "Third, because this large retrospective cohort did not include reliable RECIST (response evaluation criteria in solid tumors) data for all patients, we did not investigate the correlation between KRAS mutational status and tumor response according to RECIST criteria." (PMID 31600989, 2019). "In addition, patients with CRC with normal KRAS may respond differently to immunological therapies according to the location of the tumor, which suggests that the immune responses and tumor evolution in the right and left colon may be different." (PMID 31281317, 2019). "Furthermore, xCT knockdown significantly ablated the growth of colonies in soft agar, as well as the growth of tumor xenografts established from KRAS-transformed cells, which correlated with increased oxidative stress and decreased levels of intracellular GSH43." (PMID 31852884, 2019). "Thus, HSP90/AXL/eIF4E-regulated UPR that underpins adaptive resistance to MTA and trametinib also regulates intratumor heterogeneity of KRAS-mutant lung tumor cells that occurs under pathological conditions, extrapolating our findings to a generalized principle that governs tumor progression." (PMID 31431614, 2019). "The high frequency of KRAS mutations in our patient cohort is consistent with published data on PDAC cases when sensitive detection methods are used and indicated that we had obtained the desired enrichment of tumor cells by manually dissecting regions of interest from the FFPE sections." (PMID 30611220, 2019). "For example, it was described that KRAS mutation is associated with suppressed Th1/cytotoxic immunity in CRC, whereas another work demonstrated that pathway mutations such as those in the RAS/RAF or PI3KCA pathways are associated with different expression of tumor leucocyte fraction." (PMID 31036005, 2019). "Our results show that DSF co-treatment with: a) MEK inhibitors may enhance tumour suppression; b) OxPt in CRC may counteract impaired response to cetuximab by KRAS/BRAF mutations and c) as a single treatment, TTM may be less effective than DSF and decreases the efficacy of the latter." (PMID 30792807, 2019). "No BRAF or KRAS mutation was detected in cfDNA from patients with wild‐type tumor tissue." (PMID 31134762, 2019). "Finally, a catalytic light chain of botulism toxin E protease engineered to cleave SNAP23 suppresses in vivo tumorigenesis by KRAS-driven tumor cells, indicating that vesicular transporters may provide a therapeutic opportunity in KRAS-dependent malignancies." (PMID 31712554, 2019). "Because non-canonical Wnt signaling reduces activation of canonical Wnt signaling pathways, these studies consistently show that KRAS activates canonical Wnt signaling to support stem-like properties of cancer cells and tumor growth and that this node may be targeted for cancer therapy." (PMID 31681559, 2019).
tumor (continued). "The strong upregulation of KRAS in T1 (at a mutation rate 86%, in stark contrast to the WES predicted frequency of 32%) might indicate a massive activation of the MEK/ERK signaling pathway in this patient’s tumor." (PMID 31805664, 2019). "However, this explanation is not applicable for the comparison of KRAS mutations between primary tumor and its lymph node metastases." (PMID 30368666, 2019). "However, the comparison between the MAF of KRAS in ctDNA and tumor tissue was rarely reported." (PMID 31850201, 2019). "The discrepancy between EBC and tumor as well as between blood and tumor was noted when KRAS mutation status (including the wild, not mutated sequence) detected in EBC and blood differed from mutation (or mutations) observed in corresponding set of five cancer tissue samples." (PMID 30368666, 2019). "With respect to other pathways associated with oncogenic KRAS activity in the lung, the therapeutic targeting of PI3K has been plagued by dose‐limiting toxicities that prevent the use of high concentrations of inhibitors needed to penetrate the tumor and execute anti‐cancer activity." (PMID 30833304, 2019). "A morphologic continuum between the high-grade and the low-grade tumors was observed in four cases; the same KRAS mutations were found in both the SBT/APST and HGSC component of the tumor, indicating a clonal relationship and suggesting that in rare cases, HGSC may arise from SBT/APST14." (PMID 31807285, 2019). "In this regard, it is important to stretch that the specificity regarding KRAS that has emerged in the current meta-analysis reflects the correlation existing between the primary tumor tissue and the LB, and not the overall specificity of KRAS mutational status for PDAC diagnosis." (PMID 31405192, 2019). "Thus, miR-134 may act as a tumor suppressor in cell proliferation and epithelial–mesenchymal transition through the KRAS/ERK pathway." (PMID 29535681, 2018). "Multivariate Cox proportional hazard analyses incorporating primary tumor anatomic site, type of perioperative chemotherapy, treatment year, or mutational data, including KRAS mutation, BRAF mutation, or MSI, did not independently contribute to prognostication in our cohort." (PMID 29728604, 2018). "Notably there were no mutations detected in APC and KRAS in 3 metastatic samples although primary tumours from the same patients were carrying mutations in this genes." (PMID 30231850, 2018). "High MTV is associated with KRAS mutation and poor postoperative outcomes in patients with ICC, suggesting that the MTV of ICC measured by 18F-FDG-PET may provide useful information for tumor molecular profiles and prognosis." (PMID 29642912, 2018). "These analyses revealed no KRAS/BRAF/GNAS/PIK3CA mutations in all tumor samples." (PMID 30116990, 2018). "Interestingly, in our subsequent experiments in vivo performed in a panel of PDXs bearing KRAS mutations, we confirmed that this compound is very active against this tumor population for which no clinically effective therapy currently exists." (PMID 29534749, 2018). "In this context, there is evidence that c-RAF inhibits apoptosis in a kinase-independent manner, apparently thorough Bcl-2 and pro-apoptotic kinases ASK1 and MST2; in line with this hypothesis, c-RAF inhibition in KRAS-mutant tumor cells induces activation of Caspase-3." (PMID 30060526, 2018). "Tumor samples were analysed using NGS while BEAMing (digital PCR technology combines emulsion PCR with magnetic beads and flow cytometry for the highly sensitive detection and quantification of mutant tumor DNA molecules) has been used to search for KRAS and NRAS mutations in plasma samples." (PMID 30008744, 2018). "Interestingly, when both tumour origin and HPV status were taken into account, the rate of KRAS mutations was significantly lower in anal gland/transitional-type neoplasms (8/24, 33.3%) (especially in HPV-positive tumours (2/10, 20%)) compared to their colorectal-type counterparts (24/44, 54.5%)." (PMID 29700411, 2018).
tumor (continued). "Therefore, the identification of genes that work in concert with KRAS to drive tumor progression and/or metastasis provide the greatest hope of improving patient outcomes through personalized treatment options, either by acting as a direct target or targeting converging signaling pathways." (PMID 30013058, 2018). "The prognostic value of KRAS mutations in ctDNA but not tumor tissue was repeatedly confirmed." (PMID 29441349, 2018). "In addition, Ktrans and kep histogram parameters showed difference according to the KRAS mutation, demonstrating the utility of the histogram of perfusion parameters derived from DCE-MRI as potential imaging biomarkers of tumor characteristics and genetic features." (PMID 30186857, 2018). "In addition to human studies correlating elevated MYC levels with worse clinical outcomes, disease progression, and metastasis, in animal models, spontaneous metastatic spread and rapid tumor progression is observed in KRAS mutant tumors with exogenous MYC62,63." (PMID 30013058, 2018). "Hence, the results of this study portrays that KRAS status might be used as a predictive factor in relation to the efficacy of antibody-chemotherapy and it highlights the increasing importance of tumor biomarker analysis as an element of therapy selection." (PMID 29484148, 2018). "Interestingly, the KRAS mutant alleles, which emerge at the time of disease progression, decline at the suspension of anti-EGFR therapy, thus indicating the dynamic mode of the tumor cell population that was confirmed in experimental models." (PMID 29534749, 2018). "KRAS-specific IgG may, therefore, serve as a readout of the activation of both arms of the anti-tumor adaptive immune armament although some B-cell populations may promote tumor progression." (PMID 30283732, 2018). "No additional KRAS mutations were detected by ddPCR and the detection rate of tumor-specific mutations in samples, where both MassARRAY and ddPCR analyses were done, was higher with the MassARRAY technique (10/19, 52.6% for iPLEX, 14/19, 73.7% for UHS) than with ddPCR (8/19, 42.1%)." (PMID 28459822, 2017). "Of the 26 patients with detected mutations in both the CTC and the primary tumor, 15 (58%) patients had at least one matching mutation (CTC + Tumor KRAS match), while in 11 (42%) patients, the KRAS mutations differed between the CTCs and the tumor (CTC + Tumor KRAS unmatch)." (PMID 28674438, 2017). "Likewise, ERK inhibitor which down-regulated the PD-L1 expression unleashed the T cells’ potence to kill KRAS-mutant tumor cells in the co-culture system but 100 nM ERK inhibitor itself could not affect the survival of H358 cells." (PMID 28451792, 2017). "Furthermore, FOSL1 genetic inhibition is detrimental to both KRAS-driven tumour types." (PMID 28220783, 2017). "Interestingly, for sample OV10, the KRAS variant was only called in the tumor/normal analysis but not in tumor only analysis." (PMID 28852190, 2017). "When it comes to targeted drugs directed specifically towards the tumour cells in CRC, the EGFR antibodies cetuximab and panitumumab are now often routinely added to the chemotherapy in advanced CRC, if the tumour cells are not harboring any KRAS or BRAF mutation." (PMID 29262612, 2017).
tumor (continued). "Here, we report the case of a PDAC patient with an unusual clinical course: the tumor of the patient harbored a wildtype KRAS gene at the time of initial PDAC diagnosis; however, upon disease progression 4 years later, a mutation within exon 2 of the KRAS gene was detectable." (PMID 28549417, 2017). "KRAS mutation status and tumor location were not a prognostic factor for survival." (PMID 29085005, 2017). "However, the rate of cfDNA mutations in the patients without any prior KRAS/NRAS/BRAF/PIK3CA tumor mutations was 10-fold lower than the cutoff (0.002% ± 0.00014; N = 374)." (PMID 27852040, 2017). "The high numbers of non-responders could, at least in part, be due to intratumoral heterogeneity of KRAS mutations that are not included in the tumor areas analysed." (PMID 28636636, 2017). "NRAS‐mutation(+) CRC significantly correlated with older age, distal colon, more mucinous component of the tumor, earlier AJCC stage, less lymph node metastasis, and less lymph vessel invasion (P = 0.01, 0.002, 0.02, 0.001, 0.003, and 8 × 10−6, respectively), compared with KRAS‐mutation(+) CRC." (PMID 28378457, 2017). "The high precision/low sensitivity for KRAS indicated that a KRAS variant detected by the cfDNA-based NGS assay is likely present in the tumor tissue, although the absence of a KRAS variant in cfDNA does not necessarily imply a lack of KRAS mutations in tumor tissue." (PMID 29137355, 2017). "Because of the rarity of this observation, it is not clear whether the concomitant KRAS and BRAF mutant tumors have a different biology and natural history than singly KRAS or BRAF mutant tumors, or which of the two mutations play the dominant role in driving the tumor proliferation." (PMID 28580315, 2017). "Using the short term ex-vivo treatment protocol we established that: 1) 3 μM of Selumetinib inhibits pERK1/2 phosphorylation in all tumours and the effect is independent of whether or not tumours harbour a KRAS or BRAF mutation." (PMID 28931905, 2017). "Nonetheless, despite the central role of the mitotic machinery to mutant KRAS phenotype, the contribution of other members of the FOSL1 signature to the effect induced by FOSL1 loss remains unexplored and may also help to explain the impact of FOSL1 inhibition in homeostasis of mutant KRAS tumours." (PMID 28220783, 2017). "However, the molecular mechanisms whereby oncogenic KRAS regulated AURKA expression and its clinical and functional role in KRAS-driven tumours were largely unknown." (PMID 28220783, 2017). "CA 125 level did also significantly differ with KRAS mutation status (Mann-Whitney’s test, mean rank 46.41 for KRAS mutation negative and mean rank 60.89 for KRAS mutation positive, p = 0.02) but not for the other tumor markers (Mann-Whitney’s test, p-values from 0.1 to 0.9)." (PMID 29049328, 2017).
tumor (continued). "Hence, high sensitivity in relation to KRAS mutation assays is crucial in minimizing the risk of false negative results in tumor specimens containing low quantities of mutated DNA." (PMID 29137388, 2017). "The biological correlation pattern between BRAF and KRAS might depend on tumor location." (PMID 28623901, 2017). "Additionally, in Round 3, each tumour sample was classified as having been tested for either RAS or KRAS based exclusively on the information recorded in the oncologist notes; the classification was not based on the specific exons and codons tested by the pathologist as this is often not recorded." (PMID 29183279, 2017). "Of the 4 patients with tumor tissue KRAS mutations but no cfDNA KRAS mutations, one of them had a low cell-free DNA yield (1.7 ng), while the other three had high yields (>8 ng) that were similar to the two patients with KRAS mutations detected in both plasma and tumor tissue." (PMID 29137355, 2017). "Let-7 family has several members, recent studies have found that the Let-7 could function as a tumor suppressor during the development of solid tumors through inhibiting cancer proliferation by targeting some oncogenes/antioncogenes, including KRAS gene Chun-Yan Deng." (PMID 28099923, 2017). "KRAS mutations were present in only 4% of the tumours and had no prognostic impact." (PMID 26844548, 2016). "Thus, the MST/Hippo pathway seems to have several roles in KRAS-dependent tumours." (PMID 27322327, 2016). "KRAS exon 2 tumour mutation status was evaluable in tumours from 25 of the 44 enrolled patients (results were not available for 19 patients, either because adequate tumour tissue was not available or the patient did not provide consent to the additional analysis)." (PMID 26766738, 2016). "Moreover, the weight of tumours in the AZD5438 treated mice cohort was in general 60% less than in vehicle treated mice (p < 0.01, t-test), suggesting that AZD5438 could inhibit a KRAS mutant tumour in vivo." (PMID 26881434, 2016). "However, the same KRAS mutation was identified only in 1/8 plasma samples, whereas in two additional patients a KRAS mutation was found in the plasma but not in the tumor tissue." (PMID 27448974, 2016). "A limitation of this meta-analysis is only six studies investigated KRAS mutation, as further studies are necessary to answer important questions and a large sample size is a pre-requisite for assessing the association of KRAS mutation with MSI along with other tumor molecular characteristics." (PMID 27120810, 2016). "Finally, higher CD20 expression was more often present in KRAS wild-type tumours (p = 0.027)." (PMID 27048364, 2016). "On their own, the mutant KRAS transgene and the axin mutation cause intestinal epithelial hyperplasia and increase epithelial cell proliferation, respectively, in zebrafish larvae, but do not cause cell invasion or neoplasia." (PMID 26893369, 2016). "Moreover CD138 expression was found be significantly higher in KRAS wild-type tumours." (PMID 27048364, 2016). "Finally, vigorous tumor progression is paralleled by the occurrence of vast numbers of mutant alleles in the plasma (EGFR mutations in patients 2, 11, 13, and 14, as well as, KRAS mutations in patient 12)." (PMID 27640882, 2016). "While 24 of 112 tumor samples showed intermediate-methylation epigenotype significantly correlating with KRAS-mutation(+) (P=3×10-4), 88 tumor samples showed low-methylation epigenotype correlating with the absence of KRAS- and BRAF-mutations." (PMID 27563825, 2016). "Additionally, KRAS overexpression attenuated the suppressive effect of miR-16 on tumor growth, suggesting that miR-16 may inhibit tumor growth by silencing KRAS." (PMID 27857191, 2016). "Both tumor nodules are negative for KRAS and EGFR mutations (data not shown)." (PMID 27597976, 2016).